SMAD4 (SMAD family member 4)
Diseases named in the same sentence as SMAD4 in open-access papers (continued):
Sharing a sentence is not in itself a finding about the gene and the disease.
pancreatic cancer (continued). "Previous studies have shown that expression of SMAD4 SNP or TGF-βR2/SMAD4 tumor protein in relation to the TGF-β pathway in pancreatic cancer can be utilized in clinical trials of targeted therapies." (PMID 30359281, 2018). "Smad4/DPC4 is an essential transcription factor in the TGF-β pathway and is frequently mutated or deleted in prostate, colorectal, and pancreatic carcinomas." (PMID 29102676, 2018). "This was dependent on Smad4 and the tumor suppressive function of TGFβ in a mouse model of pancreatic cancer." (PMID 28086235, 2017). "Homozygous deletion of Smad4 is found in about 30% of pancreatic cancer patients, inactivation of Smad4 in 20% of patients, and allelic loss of its chromosome is found in 90%." (PMID 28067794, 2017). "Considering that half of pancreatic cancers and more than 20% of colon cancers show deletion of Smad4, inhibition of PAK1 would be one of plausible strategy for treatment of human cancers such as pancreatic cancer and colon cancer." (PMID 28423593, 2017). "In a pancreatic cancer mouse model, Smad4−/− tumors metastasized more frequently than Smad+/+ tumors." (PMID 28067794, 2017). "We additionally evaluated the EMT marker genes, E-cadherin and vimentin, with two pancreatic cancer cell lines, SMAD4-intact SU.86.86 and SMAD4-homozygously-deleted BxPC3." (PMID 28638102, 2017). "Once phosphorylated, R-Smads associate with the common Smad, Smad4, also known as DPC4 (deleted in pancreatic cancer 4), and mediate nuclear translocation of the heterotetromeric complex." (PMID 28067794, 2017). "The important role of Smad4 in triggering AGR2 downregulation in human pancreatic cancer cells exposed to TGF-β has recently been shown." (PMID 28810836, 2017). "It would be of interest to determine if c-Myc or SMAD4 regulates miR-29 expression in pancreatic cancer cells, as both of them have been indicated to play a critical role in PDAC." (PMID 27626694, 2016). "MiR-483-3p overexpression in pancreatic cancer cell lines significantly represses DPC4/Smad4 protein levels and simultaneously promotes cell proliferation and colony formation in vitro." (PMID 27240340, 2016). "Through targeting the promoter regions, Smad4 induces the expression of p15ink4b to inhibit the growth of pancreatic cancer cells." (PMID 27595937, 2016).
pancreatic cancer (continued). "Transfection of Smad4 into pancreatic cancer cells reduces the anchorage-independent growth by more than 50%, and inhibits xenograft tumor growth." (PMID 27595937, 2016). "The DPC4 encoded Smad4 protein is a central mediator of transforming growth factor (TGF)-β signaling and mutated in approximately 50% of invasive pancreatic carcinomas." (PMID 27916875, 2016). "The tumor suppressor Smad4/DPC4 is an essential transcription factor in the TGF-β pathway and is frequently mutated or deleted in prostate, colorectal, and pancreatic carcinomas." (PMID 27308538, 2016). "For example, nearly 100% of pancreatic tumors have a mutation in at least one of the TGF-β pathway genes, and over 50% have gene deletion in SMAD4 (DPC4)." (PMID 26172047, 2015). "Secondly, overexpression of miR-301a-3p down-regulated SMAD4 at the mRNA and protein levels in pancreatic cancer cell lines, and vice verse." (PMID 26019136, 2015). "Conspicuously, we notice that 5 genes (CDK6, E2F3, CCND1, SMAD4 and CDKN1B) are associated with cell cycle, colorectal cancer, pancreatic cancer, chronic myeloid leukemia, and small cell lung cancer in the cluster of Group A." (PMID 26221171, 2015). "The TGF-b signalling pathway, which inhibits growth, is deregulated in a large proportion of pancreatic cancers and associated with underexpression of TGF-b receptors and mutation of the SMAD4/DCP4 gene." (PMID 25301978, 2014). "Mutations in SMAD4 have been reported to frequently co-exist with KRAS mutations in colorectal cancer, and studies in pancreatic cancer suggest that wildtype SMAD4 blocks progression of KRAS G12D-initiated tumors." (PMID 25523272, 2014). "Since Smad4 is critically involved in TGFβ1 signaling, it is reasonable to assume that there is a close link between these calcium binding proteins and TGFβ1 in pancreatic cancer." (PMID 24670043, 2014). "The relationship between clinical parameters (reported in more than 2 studies) and Smad4 staining was explored in gastric cancer, colorectal cancer and pancreatic cancer." (PMID 25333693, 2014). "The human pancreatic cancer cell line, BxPC3, has been reported to be Smad4-null due to a homozygous deletion and has been widely used as a Smad4-null model." (PMID 24944686, 2014). "There are limited data regarding TGF-β receptor and SMAD4 expression or their prognostic significance in advanced pancreatic cancer patients." (PMID 24465802, 2014). "Deletion of chromosome 18q, which encompasses the Smad4 region, significantly affects the prognosis of pancreatic cancer." (PMID 24944686, 2014). "We previously reported that TGF-β was unable to rescue BxPC3 cells from rapamycin-induced cell death, as was the case in the Smad4 wild-type Panc1 pancreatic cancer cells indicating that BxPC3 pancreatic cancer cells are not responsive to TGF-β." (PMID 24944686, 2014). "SMAD4 is also considered a tumor suppressor gene that was originally recognized as “deleted in pancreatic carcinoma locus 4” (DPC4) on chromosome 18q21.1." (PMID 25264609, 2014). "The SMAD4 gene, also known as DPC4 (deleted in pancreatic carcinoma, locus 4) is located on chromosome 18q21 and is inactivated in approximately 50–60% of PDAC." (PMID 24624093, 2014). "Our lab showed that HDACi Belinostat induced the expression of epigenetically silent TGFβ RII and therefore restored TGFβ signaling-mediated cell growth inhibition in Smad4 wild type (wt) pancreatic cancer cells (e.g., Miapaca-2)." (PMID 23922886, 2013).
pancreatic cancer (continued). "Pancreatic cancer is closely associated with the TGF-β/Smad pathway, and Smad4 is inactivated in nearly 60% of pancreatic cancer." (PMID 23418461, 2013). "The SMAD4 gene is notable primarly for the reason that immunohistochemical labeling for SMAD4 protein expression mirrors DPC4/SMAD4 gene status in pancreatic cancers with rare exceptions." (PMID 24084722, 2013). "SMAD4, also called DPC4 (deleted in pancreatic carcinomas), suggests close relationship between loss of this gene and pancreatic cancer." (PMID 22943793, 2012). "These negative observations provide convincing evidence (with the exception of SMAD4 which missed statistical significance, p = 0.09) that this group of putative pancreatic cancer biomarkers are clinically irrelevant for prognosis." (PMID 22792233, 2012). "The aim of this study is to examine the relationship between the expression of RhoT1, Smad4 and p16 and metastasis and survival in patients with pancreatic cancer." (PMID 22860091, 2012). "In the present study, using the LOH test for pancreatic cancer diagnosis at chromosomal position 18q with SMAD4, the sensitivity and specificity of the pancreatic cancer were 78% and 57%, respectively." (PMID 23197977, 2012). "Other tissue-based markers potentially relevant for pancreatic cancer include: p21, Bcl-2 and SMAD4." (PMID 22458520, 2012). "The other study revealed that the ratio of S100A9- and S100A8- positive cells in the stroma was affected by the status of tumor suppressor protein Smad4 in corresponding pancreatic cancer cells." (PMID 22838504, 2012). "SMAD4 is inactivated in approximately 55% of pancreatic cancers, either by homozygous deletion (30%) or by intragenic mutations and loss of second allele (25%)." (PMID 23197977, 2012). "In pancreatic cancers, SMAD4 is homozygously deleted in approximately 30% of cases, inactivated in 20%, while allelic loss of the whole 18q region was found in almost 90% of cases." (PMID 22943793, 2012). "Although overall SMAD4 mutations occur at low frequency among cancers, alterations in the SMAD4 gene were found in 48% of pancreatic carcinomas." (PMID 24213498, 2012). "Smad4 was originally identified as a tumor suppressor in pancreatic cancer and later characterized as a key mediator of TGFβ signaling." (PMID 22204491, 2011). "On the other hand, Dpc4/Smad4 alterations are rare in BOP-induced pancreatic tumors in hamsters (8%)." (PMID 24212630, 2011). "SMAD4 was originally identified as a tumor-suppressor gene lost in pancreatic cancers called DPC4 (deleted in pancreatic cancer 4)." (PMID 22204556, 2011). "SMURF1 is a known inhibitor of TGFβ signaling (by promoting degradation of its receptor TGFβRI, and signaling mediator SMAD4), a pathway frequently disrupted in pancreatic cancer." (PMID 21887346, 2011). "SMAD4/DPC4 is a tumor suppressor gene, which is mutated or deleted in half of all human pancreatic carcinomas and loss of expression (LOH) has been shown to be important for the progression of gastric, cervical and colorectal cancers." (PMID 21835029, 2011). "In Smad4 null IMIM PC-2 pancreatic cancer cells, expression of the dominant active IKK2 led to EMT through increased MAPK/ERK signaling." (PMID 24281219, 2010). "Loss of Smad4 early in tumor development leads to loss of TGF-β growth inhibition and unchecked tumor growth in mouse models of pancreatic cancer." (PMID 24281219, 2010). "Another study showed that TGF-β1 suppressed PTEN expression in Smad4-null pancreatic cancer cells by activating PKCα." (PMID 20684793, 2010).
pancreatic cancer (continued). "In the same year another study identified the genetic target of these allelic losses as the SMAD4/DPC4 gene (DPC-Deleted in Pancreatic Carcinoma, locus 4)." (PMID 20565773, 2010). "Much as in other human malignancies, restoration of the WWOX gene effectively suppressed the cell growth and induced caspase-dependent apoptosis in pancreatic cancer-derived cells in conjunction with an increase in SMAD4 expression." (PMID 19352382, 2009). "Stable Smad4 reexpression in colorectal and pancreatic cancer cells was adequate to mediate tumour suppression in vivo, did not inhibit cell growth in vitro and was not sufficient to rescue TGF-β antiproliferative responses." (PMID 17997817, 2007). "SMAD4 or DPC4 (deleted in pancreatic cancer, locus 4) is a tumor suppressor gene located on the long arm of chromosome 18." (PMID 17587453, 2007). "We conclude from our results that, as has previously been shown for colorectal and pancreatic cancer cells, direct effects of Smad4 on tumour cell proliferation in cervical carcinoma cells are dispensable for Smad4-mediated tumour suppression." (PMID 17997817, 2007). "In pancreatic cancer, the DPC-4 (deleted in pancreatic Cancer-4/Smad-4) gene is inactivated in by homozygous deletion or intragenic mutation in 50% of cases." (PMID 18157915, 2007). "Stable reexpression of Smad4 in colorectal and pancreatic carcinoma cells at physiological levels was adequate to suppress tumour growth in vivo, but did not restore TGF-β responsiveness." (PMID 17997817, 2007). "It is notable that the basal expression levels (and TGF-β response) of these genes were also increased by Smad4 reexpression in Smad4-negative pancreatic carcinoma cell lines, and were reduced upon Smad4 knockdown in Smad4-positive cells." (PMID 17997817, 2007). "Moreover, the combination of gemcitabine with ferroptosis inducers has demonstrated an enhancement of cytotoxic effects in SMAD4-positive organoids, proposing a viable combination therapy for pancreatic cancer." (PMID 40427552, 2025). "GEMMs incorporating Smad4 deletion alongside KrasG12D expression, such as Pdx1-CreLSL-KrasG12DSmad4lox/lox, exhibit robust tumor progression and desmoplastic stromal responses, hallmarks of human pancreas cancer." (PMID 40829173, 2025). "Similarly, in pancreatic cancer, radiomic features have demonstrated potential in predicting KRAS and SMAD4 mutations." (PMID 40192792, 2025). "Understanding how Smad4 functions could lead to more personalized approaches for managing conditions like pancreatic cancer." (PMID 39596873, 2024). "While SMAD4 loss is not an initiator of pancreatic cancer, it can promote tumor progression usually initiated by KRAS activation." (PMID 38607041, 2024). "Interestingly, deleting the SMAD4 gene has been found to have protective effects against pancreatic cancer." (PMID 38205087, 2024).
pancreatic cancer (continued). "SMAD4 function is eliminated in most pancreatic cancer patients." (PMID 38559560, 2024). "SMAD4 is a well-known tumor suppressor gene, first identified in pancreatic cancer and called DPC4." (PMID 38689334, 2024). "However, further breakthrough studies are still needed for the therapeutic target of SMAD4/DPC4-positive pancreatic cancer." (PMID 37685308, 2023). "The first SMAD to be discovered was SMAD4 or DPC4 (deleted in pancreatic cancer 4)." (PMID 37685308, 2023). "All together, these data showed that RAB10 depletion contributed to decrease the cell fitness of SMAD4-deficient cells and that RAB10 might be a susceptibility gene in SMAD4-altered colorectal and pancreatic cancer cells." (PMID 37377893, 2023). "Nevertheless, it is clear that SMAD4 is a major factor in the EMT seen in pancreatic cancers." (PMID 36902253, 2023). "Moreover, SMAD4 inactivation correlates with the presence of metastatic disease in colorectal cancer as well as pancreatic cancer." (PMID 37377893, 2023). "The aim of our study is to investigate whether SMAD4 status is a prognostic and predictive factor in patients with pancreatic cancer receiving NAT." (PMID 37568581, 2023). "The function of SMAD4 in the EMT of pancreatic cancer cells remains controversial." (PMID 36902253, 2023). "SMAD4 is inactivated in about 55% of pancreatic cancers and acts as a tumor suppressor gene." (PMID 37304241, 2023). "SMAD4 is a tumour suppressor protein also known as DPC4 (deleted in pancreatic cancer 4)." (PMID 37790705, 2023). "The aim of this study was to investigate whether SMAD4 status could be a potential prognostic and predictive biomarker for pancreatic cancer patients receiving NAT that could possibly optimize patient care." (PMID 37568581, 2023). "It has also been reported that for patients with advanced pancreatic cancer who undergo palliative chemotherapy before resection, patients with preserved SMAD4 expression have significantly shorter progression-free survival than patients with lost SMAD4 expression." (PMID 36088360, 2022). "SMAD4, a tumor-suppressor gene, is specifically inactivated in 50–55% of pancreatic cancers." (PMID 35205719, 2022). "Increasing evidence shows that the loss or inactivation of the SMAD4 gene, a critical mediator of the transforming growth factor beta (TGF-β) signaling pathways, indicates a poor prognosis in various cancers, especially pancreatic cancer." (PMID 35264071, 2022). "However, few studies have reported the correlation between SMAD4 and gemcitabine resistance in pancreatic cancer." (PMID 36127339, 2022). "Furthermore, another murine pancreatic cancer cells line, KPC‐1199, derived from pancreatic tumor tissue of an KPCmouse (also known as FC 1199), underwent Smad4‐knockout and two individual clones were produced." (PMID 35064757, 2022). "Collectively, the analyses show that PDX models can be valuable to identify copy number variations and clonal mutations of relevance (eg, SMAD4) and that the transcriptome is coming only from the pancreatic cancer cells and not from stroma." (PMID 39131259, 2022). "Furthermore, we identified a critical role of SMAD4 in mediating the responses of pancreatic cancer cells to gemcitabine chemotherapy." (PMID 36127339, 2022).